NOX4 (NADPH oxidase 4)
Diseases named in the same sentence as NOX4 in open-access papers (continued):
Sharing a sentence is not in itself a finding about the gene and the disease.
endothelial dysfunction (74 papers, 2013 to 2025). In vascular diseases, endothelial dysfunction is a systemic pathological state of the endothelium (the inner lining of blood vessels) and can be broadly defined as an imbalance between vasodilating and vasoconstricting substances produced by (or acting on) the endothelium. "NADPH oxidases (NOXs), particularly NOX1, NOX2, and NOX4, are major sources of ROS in PH, driving endothelial dysfunction, PASMC proliferation, and vascular remodeling, all hallmarks of PAH progression." (PMID 40498015, 2025). "Nonetheless, NOX4 is implicated to have protective effects on the vasculature by preventing endothelial dysfunction in ischemic or inflammatory damage." (PMID 40700116, 2025). "These DORs were located at promoters of genes including CD74, IFI27, HLA-DMA, CASP8 and NOX4, which are associated with antigen presentation, inflammation and endothelial dysfunction." (PMID 41085167, 2025). "Previously, we had reported that already in young hypercholesterolemic mice, depletion of Nox4 caused endothelial dysfunction of the aorta which further progressed after high-fat diet feeding to a higher plaque burden in the aorta." (PMID 38790608, 2024). "By down-regulating ROS production with NOX4 inhibitors, endothelial dysfunction caused by palmitic acid induced-autophagy can be improved." (PMID 35259050, 2022). "Endothelial dysfunction caused by palmitic acid-induced autophagy was ameliorated by downregulating ROS production with NOX4 inhibitors." (PMID 35259050, 2022). "Langbein and collaborators (2016) observed in in vivo studies that the endothelial function was compromised in the thoracic aorta of mice knockout for the Nox4 gene and in a hyperlipidic diet, causing an endothelial dysfunction." (PMID 36467706, 2022). "NOX4 appears to have a protective role in the vascular system as NOX4-deficient mice developed endothelial dysfunction." (PMID 35453301, 2022). "Studies using siRNA within cultured EC implicated Nox4 as being responsible for causing oxidative damage within the endothelium, reducing EC replicative potential and causing endothelial dysfunction." (PMID 34571964, 2021). "Some animal studies showed that a genetic deficiency of Nox4 was associated with endothelial dysfunction and increased atherosclerosis burden." (PMID 32630452, 2020). "Increased generation of ROS by two isoforms of NADPH oxidase, Nox2 and Nox4, has been linked to endothelial dysfunction in the diabetic retina." (PMID 32024241, 2020). "Apart from beneficial SMC effects, endothelial dysfunction in the MFS ascending aorta was prevented by NOX4-deficiency or ROS inhibition." (PMID 30841577, 2019). "HFHSD-LE2KO increased aortic superoxide levels, which might be caused by NOX1 and NOX4 upregulation, and the endothelial dysfunction caused by the decreased eNOS phosphorylation at Ser1179." (PMID 35955653, 2022). "Moreover, NOX4 may also mediate the protective effects of PA against obesity-induced endothelial dysfunction, since Nox4 deficiency in mice has been related to reduced PA performance and exercise-derived vascular protective outcomes." (PMID 37019912, 2023). "Studies to confirm a role of NOX4 in aortic disease could be pursued by crossing Prkg1RQ/+ mice with Nox4 knockout mice; however, Nox4-deficient mice exhibit vascular abnormalities—including endothelial dysfunction and apoptosis—which would confound interpretation of results." (PMID 31387997, 2019). "The attenuation of vascular oxidative stress by NAC and the NOX2/NOX4 inhibitor prevented the impairment of EDR induced by T2D RBC-EVs, suggesting a functional role of NOX4-derived ROS in the development of endothelial dysfunction in T2D." (PMID 40111409, 2025). "NOX-driven oxidative stress (NOX1, NOX2, and NOX4) also plays a key role in Group 2 Group 3, and Group 4 PH, contributing to endothelial dysfunction, myocardial fibrosis, and structural remodeling of the right ventricle." (PMID 40498015, 2025).
endothelial dysfunction (continued). "Inhibition of COX-1 and COX-2, leading to reduced PGI2, resulted in the most pronounced endothelial dysfunction in Nox4−/− mesenteric arteries under hypoxia." (PMID 39456432, 2024). "NOX4 knockout mice show angiotensin II-mediated vascular inflammation and massive endothelial dysfunction, indicating the importance of this isoenzyme in endothelial cells." (PMID 37298303, 2023). "Corneal-endothelial diseases are characterized by enlarged cells and a change in shape, which can lead to endothelial dysfunction, similar to the senescence that occurs when NOX4 generates ROS." (PMID 37371958, 2023). "Nox4 is a generating enzyme of ROS expressed in the endothelium, levels of which increase is involved in the pathophysiology of endothelial dysfunction." (PMID 37501791, 2023). "Mechanistically, our findings suggest that this is attributed to the protective effect of RBC-derived NO bioactivity in preventing RBC NOX4-derived ROS inducing vascular oxidative stress, and in turn, endothelial dysfunction." (PMID 36681048, 2023). "Collectively, these in vitro findings suggest that liraglutide alleviates ox-LDL-induced endothelial dysfunction through GLP-1R-dependent down-regulation of the LOX-1/NOX4/NF-κB signaling pathway." (PMID 37278349, 2023). "Our results point to exosomes as a novel class of bioactive factors secreted by CD4+ T cells in immune response and represent potential important triggers of NOX4-dependent endothelial dysfunction." (PMID 36211827, 2022). "Endothelial dysfunction in the ascending aorta in a Marfan’s disease model has been prevented in mice following the knockdown of NOX4." (PMID 33744854, 2021). "The results of TUNEL, DHE, tube formation, and aortic ring assays demonstrated that downregulation of Nox4 alleviated T2DM-induced endothelial dysfunction." (PMID 33736642, 2021). "Elevated NOX4 will diminish nitric oxide bioavailability, an accepted marker of endothelial dysfunction." (PMID 29127504, 2017). "Zhang and colleagues observed that in HUVECs BBR ameliorates palmitate-induced endothelial dysfunction by upregulating eNOS and downregulating NOX4 through the activation of AMPK." (PMID 25785174, 2015). "The beneficial effects of PLC likely derived from improvement of mitochondrial β-oxidation and reduction of Nox4-mediated oxidative stress and endothelial dysfunction." (PMID 26473356, 2015). "Similarly, mesenteric arteries depleted of Nox4 and incubated with diclofenac under hypoxia revealed an amplified endothelial dysfunction." (PMID 39456432, 2024). "Diminishing Nox4 under these conditions led to endothelial dysfunction in resistance arteries." (PMID 38790608, 2024). "Moreover, miR‐146a also has a role in preventing endothelial dysfunction by inhibiting endothelial activation with increasing nitrite oxide synthase (eNOS) expression and reactive oxygen species (ROS) inhibition via NADPH Oxidase 4 (NOX4) pathway." (PMID 39392102, 2024). "However, in mesenteric arteries from Nox4−/− mice, the hypoxia-induced endothelial dysfunction was further altered." (PMID 39456432, 2024). "For example, it may protect endothelial dysfunction through inhibiting Nox4-responsive oxidative stress and ROS-sensitive NLRP3 signaling pathway under high glucose stress both in vivo and vitro." (PMID 37049509, 2023).
endothelial dysfunction (continued). "For example, saxagliptin attenuates ox-LDL-induced cytokine and vascular adhesion molecule (TNF-α, Il-1β, ICAM-1, VCAM-1) production by inhibiting AP-1 and NF-κB and reduces Nox4 expression, thereby inhibiting the excessive generation of ROS and improving endothelial dysfunction." (PMID 37660030, 2023). "NOX1, NOX2 and NOX5 are characterized by their direct involvement in the onset of inflammation, apoptosis and endothelial dysfunction, while NOX4, by contrast, is characterized as an important vasoprotective agent, involved in the suppression of cell death pathways and increased NO bioviability." (PMID 36467706, 2022). "Access to an exercise wheel prevented endothelial dysfunction in wild-type, but not Nox4−/− deficient mice fed a high fat diet." (PMID 34571964, 2021). "In mice, deletion of NOX4 subsequently promotes endothelial dysfunction, and decreases NO production, which may be attributable to its well-noted ability to increase hydrogen peroxide and decrease reactive oxygen species formation." (PMID 33228767, 2020). "NADPH oxidase 4 (Nox4) and eNOS, which are important enzymatic sources of reactive oxygen species (ROS) in diabetic vasculature, were regulated by H3K4me1, H3K9me2, and H3K9me3 resulting in endothelial dysfunction." (PMID 32070413, 2020). "Moreover, rutin, a glycoside of quercetin, protected from endothelial dysfunction through inhibition of NOX4." (PMID 32630452, 2020). "Circulating endothelial microparticles (EMPs), vesicular structures found in plasma from patients with vascular diseases so utilized as a surrogate marker of endothelial dysfunction, are oxidative stress inducers; they promote upregulation of NOX4 expression and ROS production." (PMID 25785174, 2015). "Therefore, berberine ameliorates palmitate-induced endothelial dysfunction by upregulating eNOS expression and downregulating expression of NOX4." (PMID 24385682, 2013). "Furthermore, overexpressed endothelial NOX4 has been shown to improve vasodilation and lower blood pressure in transgenic mice through the generation of H2O2, whereas NOX4 knockout mice displayed worsened angiotensin II-induced inflammation, endothelial dysfunction, and vascular remodeling." (PMID 40700116, 2025). "Therefore, blocking ox-LDL-induced endothelial dysfunction mediated by the LOX-1/NOX-4/ NF-κB pathway may serve as a therapeutic strategy for the treatment of ASCVD." (PMID 37278349, 2023). "Considering the observed role of RBC NOX4-derived ROS in development of a vascular arginase-dependent endothelial dysfunction, we can speculate that in the present model vascular arginase is upregulated via ROS, stimulated by a lack of RBC-derived NO bioactivity." (PMID 36681048, 2023). "Endothelial dysfunction is not only characterized by reduced NO bioavailability and another important fact is the increased expression of NOX1, NOX2 and NOX5, associated with inflammation, and reduced production of vasculature-protective biomolecules, such as the product catalyzed by NOX4." (PMID 36467706, 2022). "Therefore, NOX4-induced endothelial dysfunction may be an important contributor to vascular pathology and renal disease severity/progression in PKD." (PMID 32183375, 2020). "GLX351322, a selective inhibitor of NOX4, has been suggested to be effective in T2D, while Plumbagin, another Nox4 specific inhibitor, has been reported to counteract oxidative stress-induced endothelial dysfunction and preadipocyte apoptosis under hyperinsulinemic conditions." (PMID 32630452, 2020).
endothelial dysfunction (continued). "Collectively, these data indicate a novel role for endothelial MR to regulate COX2 and NOX4 in female mice, which may be key mediators of aldosterone-induced endothelial dysfunction and vascular contractility in mechanisms in females, warranting future investigation." (PMID 33228767, 2020). "Thus, NOX4 induced Nrf2 activation is protective against endothelial dysfunction." (PMID 29930512, 2018). "Mice lacking a specific NOX isoform or subunit, either NOX1, NOX2, NOX4, 22phox, p47phox, or NOXA1, exhibit less endothelial dysfunction and less severe HTN induced by acute Ang II infusion." (PMID 39765782, 2024). "DMB treatment reduced both NADPH oxidase activity and NOX-4 transcript levels, suggesting that TMAO regulated NADPH-driven ROS production to induce endothelial dysfunction." (PMID 35052589, 2021). "Therefore, the objective of this study was to determine the main sources of ROS in early PKD and whether NOX4-induced oxidative stress results in EC mitochondrial abnormalities and contributes to endothelial dysfunction, vascular abnormalities, and renal disease progression." (PMID 32183375, 2020). "In conclusion, RES improved endothelial dysfunction, ECM degradation and SMC death by alleviating oxidative stress (eNOS/iNOS balance; NOX4 and ROS), MMP2 and the miR-29b/miR-21 balance, respectively." (PMID 30841577, 2019). "FENDRR influences endothelial dysfunction by promoting cell apoptosis and inhibiting cell proliferation and migration through the miR‐423‐5p/Nox4 axis, with miR‐423‐5p acting as a target of FENDRR and Nox4 as its downstream target." (PMID 40066229, 2025). "GLP-1 RAs also downregulate the NLRP3 inflammasome complex, a critical mediator of high glucose-induced endothelial dysfunction, by suppressing NLRP3, ASC, and caspase-1 expression and reducing oxidative stress via the inhibition of NADPH oxidase 4 (NOX4) in human umbilical vein endothelial cells." (PMID 40807170, 2025). "Loss of Nox4-derived H2O2 can be partially compensated for by nNOS upregulation, but severe endothelial dysfunction is not reversible." (PMID 38790608, 2024). "Mice lacking NOX1, NOX2, NOX4, or p47phox display less endothelial dysfunction and severe HTN when exposed to acute Ang II infusion." (PMID 39765782, 2024). "In one study, NOX4, but not NOX1 or NOX2, is implicated in septic manifestations of acute lung injury and endothelial dysfunction." (PMID 38966542, 2024). "Simultaneous inhibition of NOX2&4, and sole inhibition of NOX4 both prevented eNOS KO RBC-induced endothelial dysfunction in WT aortae (respectively), but had no impact on EDR on WT vessel co-incubated with WT RBCs." (PMID 36681048, 2023). "Next, ox-LDL-induced HUVECs were treated with GKT137831; Nox4 inhibitor, 4-PBA; ER stress inhibitor, N-acetylcysteine; ROS scavenger, and AICAR; AMPK activator to show the involved mechanism of AGE and decursin against endothelial dysfunction." (PMID 38095615, 2023). "Our findings suggest that ApoE−/− mice develop endothelial dysfunction in the aorta by increased oxidative stress via the involvement of LOX-1, NOX1, and NOX2, whereas NOX4 may participate in media remodeling." (PMID 37873768, 2023). "NOX2 and NOX4 are two subtypes of NADPH oxidase, are mainly expressed in endothelial cells, and participate in the generation of ROS, superoxide, and hydrogen peroxide, all of which promote endothelial dysfunction." (PMID 36421426, 2022). "Taken together, the results indicate that downregulation of Nox4 by HDAC3 inhibition protected against T2DM-induced endothelial dysfunction through a mechanism involving Nrf2 and the activation of the Nrf2–Nox4 negative feedback loop." (PMID 33736642, 2021).
endothelial dysfunction (continued). "This study was designed to investigate the effects of miR-363-3p on endothelial dysfunction and the inflammatory response in CHD based on a hypothesis involving molecular targeting of NOX4 via the p38 MAPK signaling pathway." (PMID 33744854, 2021). "Phenolic extracts derived from RB down-regulated the expression of four genes, ICAM1, CD39, CD73 and NOX4 and up-regulated the expression of another four genes, Nrf2, NQO1, HO1 and eNOS, indicating an antioxidant/ anti-inflammatory effect for RB against endothelial dysfunction." (PMID 31547608, 2019). "Interestingly, NOX4 protein expression was upregulated in the media, but not in the endothelium of the ApoE−/− mouse aorta, suggesting that NOX4 did not contribute to endothelial dysfunction." (PMID 37873768, 2023). "Notably, sulodexide prevented hyperglycemia-induced overexpression of NOX4 and NOX5, suggesting that this may be a mechanism that prevents excessive ROS generation and endothelial dysfunction." (PMID 36829947, 2023). "Indeed several studies have shown that mice lacking NOX4 had increased inflammation, hypertrophy of the medial layer in the blood vessels and endothelial dysfunction." (PMID 29930512, 2018). "Also, by studying endothelial dysfunction, the absence of Nox4 resulted in reduction of endothelial nitric oxide synthase expression, nitric oxide production, and heme oxygenase-1 expression, which was associated with apoptosis and inflammatory activation." (PMID 25880434, 2015). "Indeed, decreased vascular inflammation and oxidative stress may be the mechanism by which the oil mixture treatment attenuates endothelial dysfunction in aged rats, as it significantly reduced the arterial expression of pro-inflammatory enzymes like COX-2 and prooxidant enzymes like NOX-4." (PMID 32503213, 2020). "Also, immunoreactivity to LOX-1 and NOX2, but not to NOX1 or NOX4 was elevated in retinal vessels of ApoE-/- mice, suggesting that a mechanism involving LOX-1, NOX2, and ROS may be involved in mediating endothelial dysfunction." (PMID 31781340, 2019).